CLDN7 (claudin 7)
Diseases named in the same sentence as CLDN7 in open-access papers (continued):
Sharing a sentence is not in itself a finding about the gene and the disease.
colitis (26 papers, 2011 to 2025). Inflammation of the colon. "Our previous research highlighted a significant down-regulation of Cldn-7 expression in UC; additionally, Cldn-7 deficiency led to spontaneous colitis, increasing susceptibility to dextran sulphate sodium (DSS)-induced epithelial injury." (PMID 38654000, 2024). "Given that the mucus barrier is an important factor in protecting the intestinal epithelium from bacterial invasion, we used AB-PAS staining and immunohistochemistry to detect the effect of Cldn7 deficiency on the intestinal mucus layer of mice with colitis." (PMID 35039003, 2022). "Recently, the role of Cldn7 was mechanistically demonstrated by Cldn7 knockout mice; loss of Cldn7 promotes colitis and subsequent malignant transformation by disrupting tight junction integrity and increasing the inflammation." (PMID 35956407, 2022). "The activation of TRPV4 in the gastrointestinal tract causes experimental colitis in mice, which also causes the downregulation of claudin-7 and changes in tight junction morphology." (PMID 35028313, 2022). "The results of AP-PAS staining showed that the Cldn7 deficiency caused the intestinal mucosal structure disorder in mice with colitis, and observably reduced the number of goblet cells and mucins." (PMID 35039003, 2022). "Compared with the controls, Cldn7 knockout increased susceptibility to colitis, including greater degree of weight loss, colon shortening, and a significantly higher disease activity index score." (PMID 35039003, 2022). "Compared with that in CreW mice treated with DSS, CreERT2 mice showed a higher abundance of E. coli, indicating that Cldn7 knockout would cause a significant increase in the abundance of this species during DSS-induced colitis." (PMID 35039003, 2022). "Studies have shown that mice with colon claudin-7 deficiency develop fatal colitis shortly after birth." (PMID 33727402, 2021). "Accordingly, antibiotics ameliorated colitis in mice with claudin 7 deficiency, whereas addition of bacterial antigen (fMLF) reversed this protective effect." (PMID 28707083, 2017). "As TJs play an essential role in the epithelial barrier, IEC-specific deletion of Claudin-7, a predominant intestinal claudin, enhances paracellular permeability and causes spontaneous colitis in mice." (PMID 27229483, 2016). "We found that DSS-induced colitis was associated with decreased expression of colonic claudin-1, claudin-3, claudon-5, claudin-7 and claudin-8, and also increased expression of colonic claudin-2." (PMID 22073304, 2011). "One study revealed that mice deficient in claudin 7 developed fatal colitis shortly after birth." (PMID 40292216, 2025). "Additionally, these Cldn-7 knockout models exhibited heightened susceptibility to experimental colitis, limited epithelial repair and regeneration, and increased differentiation toward the secretory lineage." (PMID 38654000, 2024). "CLDN7 is associated with colitis according to several authors." (PMID 37512030, 2023). "AB-PAS staining and immunohistochemical staining of Muc2 mucin were used to detect the effect of Cldn7 deficiency on the mucus layer of mice with colitis, and fluorescence in situ hybridization was used to detect how Cldn7 promotes spatial separation of the gut microbiota from the host." (PMID 35039003, 2022). "For example, mice deficient in claudin 7 in the colon develop lethal colitis soon after birth." (PMID 28707083, 2017). "Mice deficient for Cldn7 were reported to suffer from spontaneous development of colitis." (PMID 24278294, 2013). "Therefore, we investigated whether the intestinal barrier caused by the loss of Cldn7 would affect microbial invasion and thus promote the development of colitis." (PMID 35039003, 2022). "Our results indicated a decrease of crotonate in plasma from IBD patients, and crotonate supplementation effectively alleviated experimental colitis via the ACSS2‐H4K12cr‐CLDN7 axis." (PMID 40650658, 2025).
colitis (continued). "Nobiletin can attenuate dextran sodium sulfate-induced intestinal barrier damage via the HNF4α-Claudin-7 signaling pathway and can cure experimental colitis by reducing inflammation and restoring the damaged intestinal barrier." (PMID 39865231, 2025). "In the present study, an experimental colitis model was established by administering DSS through drinking water; this enabled us to explore the role and mechanisms of ISC-specific Cldn-7 deficiency in colitis and colonic epithelial regeneration." (PMID 38654000, 2024). "Similar results were observed in colitis-induced tissues, where transcription levels and protein levels of Wnt and Notch signalling pathway-related factors were significantly reduced after Cldn-7 depletion." (PMID 38654000, 2024). "Our previous research has demonstrated that Cldn-7 expression is reduced in human IBD samples and experimental colitis tissues in mice, with the loss of Cldn-7 inhibiting the maintenance of small ISCs and multilineage differentiation." (PMID 38654000, 2024). "Of note, Mmp7 has recently been shown to degrade the tight junction protein claudin-7 in the colon of a mouse model of colitis, leading to increased bacterial translocation." (PMID 37039638, 2023). "Claudin-1, claudin-4 and claudin-7, which are normally expressed in the colon for TJ sealing, are observed reduced in acute colitis, CD and colitis patients." (PMID 36767519, 2023). "Claudin-7-knockout mice experience antigen leak from the gut and succumb to severe spontaneous lethal colitis soon after birth." (PMID 37239907, 2023). "Colitis model was established based on inducible intestinal conditional Cldn7 gene knockout mice (Cldn7fl/fl; villin-CreERT2), by feeding with dextran sodium sulfate (DSS)." (PMID 35039003, 2022). "Although Cldn7 is considered to be related to maintaining the intestinal epithelial permeability and inhibiting colonic inflammation, we lack an understanding of how Cldn7 modulates the intestinal microbiotaand thus affects the development of colitis." (PMID 35039003, 2022). "In this study, we used dextran sulfate sodium (DSS) administration to establish experimental colitis in inducible conditional Cldn7 knockout mice." (PMID 35039003, 2022). "Mouse models with altered expression of specific claudin genes either develop spontaneous mucosal inflammation (CLDN7 knockout) or exhibit enhanced (CLDN1 overexpression, or CLDN2 knockout) or reduced (CLDN2 overexpression) susceptibility to induced colitis." (PMID 35805947, 2022). "MMP-7 antibody significantly ameliorated colonic inflammation and Claudin-7 reduction in 2 different rodent models of colitis." (PMID 36275703, 2022). "Our aim was to experimentally examine the effect of Cldn7 deletion on intestinal microbiota in colitis." (PMID 35039003, 2022). "The expressions of colonic claudin-1, claudin-3, claudin-5, claudin-7 and claudin-8 in colitis mice were markedly decreased as compared with control mice." (PMID 22073304, 2011). "Treated with CXCR4 antagonist AMD3100 significantly promoted colonic claudin-1, claudin-3, claudin-5, claudin-7 and claudin-8 expressions, and also decreased colonic claudin-2 in colitis mice." (PMID 22073304, 2011). "Intensity of claudin-7 and claudin-8 immunostaining was markedly decreased in colitis group, and moderately elevated after treatment with AMD3100." (PMID 22073304, 2011). "Therefore, claudin 7 may regulate the permeability of small molecules, and its dysfunction can increase gut permeability, promoting the passage of luminal antigens through the epithelial barrier, leading to “leaky gut”, triggering inflammation, and causing colitis." (PMID 40292216, 2025). "Here, we experimentally study the effect of Cldn7 deletion on intestinal microbiota in colitis." (PMID 35039003, 2022). "LEfSe analysis indicated that Escherichia coli may be the key bacteria in Cldn7 knockout mice during DSS-induced colitis." (PMID 35039003, 2022).
colitis (continued). "In the mouse model of experimental colitis, the lack of intestinal Cldn7 caused intestinal epithelial dysfunction and dysbiosis." (PMID 35039003, 2022). "Moreover, in the present study, we found that treated with CXCR4 antagonist AMD3100 significantly promoted colonic claudin-1, claudin-3, claudin-5, claudin-7 and claudin-8 expressions, and also decreased colonic claudin-2 in colitis mice." (PMID 22073304, 2011). "Interestingly, NaCr could alleviate colitis symptoms, increase plasma crotonyl‐CoA level and upregulate H4K12cr and CLDN7 protein levels in Acss2fl/fl mice, but exhibited no obvious effect on Acss2CKO mice." (PMID 40650658, 2025). "Notably, we established that ISC-specific Cldn-7 deficiency impairs stem cell stemness, disrupts self-renewal and differentiation, increases susceptibility to DSS-induced colitis, inhibits Wnt and Notch signalling pathways, and promotes secretory lineage differentiation." (PMID 38654000, 2024). "Furthermore, LEfSe analysis indicated that E. coli may be the key bacteria in Cldn7 knockout mice during DSS-induced colitis." (PMID 35039003, 2022). "Claudin 7 expression decreased in UC, as well as a DSS model of colitis, which is consistent with our results, but TGS 121 did not influence its expression." (PMID 33803793, 2021). "Using a Salmonella-colitis mouse model and cultured colonic epithelial cells, we found that pathogenic Salmonella colonization significantly increases the levels of claudin-2 protein and mRNA in the intestine, but not that of claudin-3 or claudin-7 in the colon, in a time-dependent manner." (PMID 23505542, 2013). "Our present study also demonstrated that AMD3100 increased the expression of colonic claudin-1, claudin-3, claudon-5, claudin-7 and claudin-8, decreased of colonic claudin-2 expression in DSS-induced colitis." (PMID 22073304, 2011). "Compared to colitis without MP, in the animals with colitis against the background of the MP consumption group, the expression of Cldn2 mRNA was slightly lower and Cldn7 was higher." (PMID 40863977, 2025). "In previous studies, we have revealed that the specific absence of Claudin-7 (Cldn-7) in intestinal epithelial cells (IECs) can lead to the development of spontaneous colitis." (PMID 38654000, 2024). "Expression of Cldn3, Cldn4, Cldn7 and Cdh1 mRNA was however not altered during colitis or due to the absence of Muc13 expression in mice." (PMID 37174625, 2023). "While Claudin-7 mRNA levels were not altered in both WT and Mmp7-/- mice, loss of Claudin-7 protein was confirmed in WT mice treated with DSS, but not in Mmp7-/- mice with DSS colitis, confirming posttranscriptional degradation of Claudin-7 by MMP-7." (PMID 36275703, 2022). "However, not all claudins protect against colitis, as demonstrated by claudin 7 deletion." (PMID 37239907, 2023). "Thus, mice lacking claudin 7, Hnf4a, and Muc2 all develop spontaneous colitis." (PMID 28707083, 2017).
lung carcinoma (24 papers, 2011 to 2025). "CLDN7 encodes a member of claudin family and were found expressed in several malignancies such as prostate cancer, lung cancer, urinary tumors, and so on." (PMID 35237298, 2021). "One example is CLDN7, a gene associated with various cancer types, including lung cancer." (PMID 40457411, 2025). "This aligns with reports that high claudin expression can confer drug resistance; for instance, claudin-7 and claudin-1/2 upregulation promotes Cisplatin resistance in pancreatic and lung cancer cells." (PMID 40508219, 2025). "CLDN7 has been shown to be downregulated in lung cancer, and when knocked down in human lung cancer cell lines, cells showed accelerated growth both in vitro and when inoculated into nude mice." (PMID 38540693, 2024). "CLDN7 is highly expressed both in the lung cancers we previously investigated as well as in the ACC and MEC cases we studied now, especially in half of the MEC tumors." (PMID 37621953, 2023). "Tested lung cancer cell lines expressed not only Cldn1, but also Cldn3, Cldn4, and Cldn7 (PC‐9 cells) or Cldn3 (SK‐Mes‐1 cells)." (PMID 31825142, 2020). "Interaction of different cell junction proteins has for example been demonstrated in human lung cancer cells, where claudin-7 and integrin β1 form a complex regulating cell growth and cell cycle progression." (PMID 31332522, 2019). "And CLDN7 was revealed to increase chemosensitivity through the activation of caspase pathway in lung cancer." (PMID 30428910, 2018). "Studies have demonstrated that CLDN7 overexpression inhibited human colon and lung cancer invasion though EMT and MAPK pathways." (PMID 30428910, 2018). "To conclude, in this study, we have discovered a novel function of claudin-7 as a basolateral protein in regulating cell proliferation and cell-matrix adhesion in lung cancer cells." (PMID 26081244, 2015). "In this study, we identified that claudin-7 co-localized and formed a protein complex with integrin β1 in human lung cancer cells." (PMID 26081244, 2015). "Both suppressing claudin-7 expression by lentivirus shRNA in human lung cancer cells (KD cells) and deletion of claudin-7 in mouse lungs lead to the reduction in integrin β1 and phospho-FAK levels." (PMID 26081244, 2015). "Our study suggests a tumor suppression role of claudin-7 in lung cancer growth and identifies a new function of claudin-7 in maintaining epithelial cell attachment through interaction with integrin β1." (PMID 26081244, 2015). "It is interesting that claudin-7 expressing human lung cancer cells have been shown to have a reduced response to HGF, are less motile, and form fewer foot processes than untreated cells." (PMID 22559840, 2012). "CLDN7 co-localizes with integrin β-1 to form a complex in lung cancer cells." (PMID 40687428, 2025). "CLDN7 is phosphorylated by protein kinase C at serine 204, and CLDN7 phosphorylation increases chemosensitivity to cisplatin treatment by activating the caspase pathway in lung cancer cells." (PMID 36620607, 2022). "For example, in lung cancer cells, claudin-7 suppresses cancer cell proliferation and increases the expression of and interacts with integrin β1 to maintain epithelial cell attachment, and these cell-matrix interactions also support cell migration and invasiveness." (PMID 34354941, 2021). "In addition, basolateral membrane claudin-7 was found to colocalize and form a protein complex with integrin β1 to maintain epithelial cell attachment and suppress cell proliferation in human lung cancer." (PMID 34354941, 2021). "In contrast, Claudin-7 was an anti-oncoprotein and expressed much lower in lung cancer tissues." (PMID 30874545, 2019). "CLDN7 increased chemosensitivity through the caspase pathway in human lung cancer cells." (PMID 29116019, 2017). "Our results suggest that claudin-7 could potentially be a tumor suppressor in lung cancer inhibiting tumor cell growth both in vitro and in vivo." (PMID 26081244, 2015).
lung carcinoma (continued). "This novel basolateral function of claudin-7 engaging integrin β1 in human lung cancer cells could provide a previously unidentified therapeutic target in the future." (PMID 26081244, 2015). "We have also knocked down claudin-7 expression in NCI-H358 (H358) human lung cancer cells." (PMID 26081244, 2015). "Similarly, claudin-7 inhibits the migration and invasion of lung cancer cells through a mechanism involving the ERK/MAPK signaling pathway." (PMID 24009024, 2013). "Furthermore, CLDN7 forms a protein complex with integrin β1 in human lung cancer cells; CLDN7 overexpression leads to greater surface adhesion in cell culture and higher expression levels of adhesion proteins, indicating that CLDN7 promotes cell–extracellular matrix adhesion via integrin β1." (PMID 39457456, 2024). "To confirm that claudin-7 is the key factor in regulating cell proliferation and cell attachment in HCC827 lung cancer cells, we transfected claudin-7 tagged with myc into the claudin-7 KD cells to investigate whether we can rescue the phenotype of claudin-7 KD cells." (PMID 26081244, 2015). "Both enhanced cell proliferation rate and decreased integrin β1 level are the primary results of claudin-7 suppression in HCC827 and H358 lung cancer cells." (PMID 26081244, 2015). "In this study, we demonstrated that knockdown of claudin-7 significantly reduced integrin β1 expression and altered its localization in HCC827 and NCI-H358 lung cancer cells." (PMID 26081244, 2015). "CLDN7 was screened out due to no specific cell proliferation phenotype was observed in lung cancer cell lines." (PMID 38629624, 2024). "Furthermore, claudin-7 inhibits cell migration and invasion through ERK/MAPK signalling pathway in response to growth factor stimulation in human lung cancer cells." (PMID 26083392, 2015). "However, CLDN7 was strongly expressed in benign bronchial epithelial cells but substantially expressed or completely absent in lung cancer cells." (PMID 36620607, 2022). "Therefore, this study aims to investigate the functional significance of this non-TJ localization of claudin-7 in human lung cancer cells." (PMID 26081244, 2015). "Our previous study demonstrates that claudin-7 is strongly expressed in benign bronchial epithelial cells with a predominant cell-cell junction staining pattern while it is either altered with discontinued weak expression or completely absent in lung cancers." (PMID 26081244, 2015). "Independent of EpCAM, it has been shown previously that Claudin-7 negatively regulates ERK activation and migration when expressed in a human lung carcinoma cell line." (PMID 30304739, 2018).